THAP3 (THAP domain containing 3)
Description:
Component of a THAP1/THAP3-HCFC1-OGT complex that is required for the regulation of the transcriptional activity of RRM1.
Tractability: PROTAC: ubiquitination databases record sites on it.
Gene: Protein-coding gene on chromosome 1 (6,624,845 to 6,635,586, forward strand). Ensembl gene ENSG00000041988.
Subcellular location (Human Protein Atlas): Nucleoplasm; Mitochondria; Nucleoli
Gene Ontology:
Molecular function: protein binding
Biological process: positive regulation of transcription by RNA polymerase II
Genetic constraint (gnomAD): Loss-of-function variants: 13 observed, 16.65 expected, observed/expected ratio (o/e) 0.78, 90% interval 0.51 to 1.24. The upper end of that interval is the gene's LOEUF score, 1.24, which puts it in group 5 of 6, group 1 being the genes least tolerant of losing a copy. Missense variants: 289 observed, 311.38 expected, observed/expected ratio (o/e) 0.93, 90% interval 0.84 to 1.02. Synonymous variants: 133 observed, 124.53 expected, observed/expected ratio (o/e) 1.07, 90% interval 0.93 to 1.23.
Homologues: Orthologues: chimpanzee THAP3 (99% identical), dog THAP3 (70% identical), mouse Thap3 (70% identical), pig THAP3 (70% identical), rat Thap3 (69% identical), rabbit THAP3 (69% identical), macaque THAP3 (66% identical), guinea pig THAP3 (59% identical), tropical clawed frog c8h14orf28 (15% identical), zebrafish si:ch211-69l10.4 (14% identical), Drosophila melanogaster CG13894 (10% identical), zebrafish si:dkey-50i6.5 (3% identical). Paralogues in human: THAP1 (24% identical), THAP2 (22% identical), THAP7 (22% identical), THAP8 (20% identical), THAP6 (13% identical), ARL14EP (10% identical), ARL14EPL (7% identical).
Diseases named in the same sentence as THAP3 in open-access papers:
THAP3 is named in the same sentence as 1 disease in open-access papers, as found by Europe PMC text mining. Sharing a sentence is not in itself a finding about the gene and the disease. The quoted sentences say what the papers report.
oligodendroglioma (1 paper, 2018). A well-differentiated (WHO grade II), diffusely infiltrating neuroglial tumor, typically located in the cerebral hemispheres. "Many of these candidates (e.g. ELTD1, SDHB, SEPW1, SLC17A7, SZRD1, THAP3, ZBTB17) are likely to push, whereas others (e.g. CAP1, HBXIP, KLK6, PARK7, PTAFR) might counteract oligodendroglioma development." (PMID 29890994, 2018). "Interestingly, several of these genes (e.g. ELTD1, SDHB, SEPW1, SLC17A7, SZRD1, THAP3, ZBTB17) are likely to push, whereas other genes (e.g. CAP1, HBXIP, KLK6, PARK7, PTAFR) might restrict oligodendroglioma development." (PMID 29890994, 2018).